CAV2 (caveolin 2)
Diseases named in the same sentence as CAV2 in open-access papers (continued):
Sharing a sentence is not in itself a finding about the gene and the disease.
lung fibrosis (5 papers, 2013 to 2022). "Except Cav1, emerging evidence showed that Cav2 was also involved in the regulation of pulmonary fibrosis." (PMID 32694556, 2020). "These experiments have established that miR-199a-5p is directly or indirectly involved in the regulation of genes previously associated with lung fibrosis: CCL2, a potent mononuclear cell chemoattractant, PLAU, a component of the fibrinolysis system, TGFBRI, the TGFβ receptor type I, MMP3 and CAV2." (PMID 23459460, 2013). "Furthermore, it inhibited the proliferation of lung fibroblasts through miR-203/Cav2, thereby preventing the excessive deposition of ECM and reducing idiopathic pulmonary fibrosis (IPF)." (PMID 35277182, 2022). "We recently reported that: (i) Cav2−/− mice, with normal levels of cav1, develop lung fibrosis over time and (ii) cav2, not cav1 drives the fibrotic process." (PMID 28352235, 2017).
melanoma (4 papers, 2014 to 2022). A malignant, usually aggressive tumor composed of atypical, neoplastic melanocytes. "Melanoma cells express channel isoforms belonging to the Cav1 (which mainly encodes high-voltage-activated L-type channels) and Cav2 (which encodes high-voltage-activated P⁄ Q-type, N-type, and R-type channels) gene families." (PMID 34575835, 2021). "Surprisingly, in another paper of the same group, Capozza and coworkers injected B16F10 cells intradermally and showed that tumor growth of B16F10 melanoma cells increases in Cav-1−/− mice and decreases in Cav-2−/− mice." (PMID 29250058, 2017). "Pearson correlation coefficient analysis was used to examine the relationship between mRNA and protein expression of ANXA1, CAV-1, CAV-2, EphA2, IGFBP2 and PTRF in the panel of melanoma cell lines." (PMID 25594008, 2014). "Sowa’s group transplanted melanoma B16F10 cells in Cav-2−/− mice and found that tumor development was strikingly inhibited in the absence of Cav-2." (PMID 29250058, 2017).
Obesity (4 papers, 2011 to 2024). Accumulation of substantial excess body fat. "The obesity-related gene phosphatase and tensin homolog was a direct target of miR-216a, which regulates expression of adiponectin receptor 1, caveolin-1, caveolin-2, and PPARγ." (PMID 35711801, 2022). "Genetic variants of ULK4, CAV2, HTRA1 and KLF12 are all associated with increased risk of stroke and the orthologous genes were upregulated in brain art ECs in obesity." (PMID 36400935, 2022).
renal cell carcinoma (4 papers, 2015 to 2022). "Loss of miRNA-218 and up-regulation of CAV2 have been observed in renal cell carcinoma (RCC)." (PMID 26112043, 2015). "CAV2 is an oncogene that can promote the growth of renal cell carcinoma through the EGFR/PI3K/Akt pathway." (PMID 33968130, 2021).
Sepsis (4 papers, 2011 to 2025). Sepsis is defined as life-threatening organ dysfunction caused by a dysregulated host response to infection. "We have demonstrated that Cav-1 and Cav-2 play important and antagonistic roles in the outcome of sepsis induced by LPS in mice." (PMID 29250058, 2017). "Cav-1−/− and Cav-2−/− mice helped to elucidate the role of caveolins in the inflammatory response in vivo, particularly during sepsis." (PMID 29250058, 2017). "As Cav-2 is not expressed in Cav-1−/− mice, we conclude that the observed effects in Cav-2−/− mice are not only due to the absence of Cav-2, supporting the idea that the balance of Cav-1 and Cav-2 activities is important for the expression of iNOS and the progress to sepsis." (PMID 29250058, 2017). "Since Cav-2 is almost completely absent in Cav-1 KO mice, the authors concluded that not just the absence of Cav-2, but also the balance between Cav-1 and -2 is important for iNOS expression and ultimately for sepsis outcome." (PMID 22229094, 2011).
triple-negative breast carcinoma (4 papers, 2008 to 2021). An invasive breast carcinoma which is negative for expression of estrogen receptor (ER), progesterone receptor (PR), and human epidermal growth factor receptor 2 (HER2). "A closer examination of 47 triple negative breast cancer cases showed a significant correlation in the expression of syndecan-2 and caveolin-2." (PMID 25623282, 2015).
bladder cancer (3 papers, 2009 to 2022). "Cav-2 is upregulated in esophageal and bladder carcinomas, which is consistent with the idea that Cav-2 could potentiate the MAPK pathway." (PMID 28338624, 2017). "Also Plk1 has been reported to be regulated by E2F3 in bladder cancer cells in addition to known E2F3 targets such as Cyclin A and novel targets including pituitary tumor transforming gene 1 (PTTG1), and Caveolin-2." (PMID 19883508, 2009).
breast tumor (3 papers, 2009 to 2024). "More specifically, high expression of CAV1 and CAV2 in stromal cells of breast tumors is associated with a more favorable prognosis, which is in line with their high expression in our good prognosis cluster." (PMID 20017941, 2009). "In our previous findings, CAV2-AU-M2 showed the ability to infect and replicate in multiple tumor cell lines (osteosarcoma and breast tumor)." (PMID 38391964, 2024). "Immunohistochemistry for syndecan-2 and its interacting partner, caveolin-2 was performed on human breast tumor tissue arrays." (PMID 25623282, 2015). "However, there is no previous evidence for involvement of a syndecan-2/caveolin-2 axis in breast tumor cell metastasis." (PMID 25623282, 2015).
hepatocellular carcinoma (3 papers, 2011 to 2025). A malignant tumor that arises from hepatocytes. "Independently, using freeze-fracture immunoelectron microscopy, Fujimoto and colleagues have shown that coexpression of Cav-1 and Cav-2 resulted in a more efficient formation of deep caveolae than Cav-1 alone in hepatocellular carcinoma cell line (HepG2)." (PMID 22229094, 2011). "For example, overexpression of Cav-2 in HepG2 hepatocellular carcinoma and siRNA knockdown in C6 glioma cell lines reduced cell proliferation." (PMID 22229094, 2011). "In hepatocellular carcinoma (HCC), TEVs enriched with Cav1 and Cav2 have been shown to induce migration and invasion in non-motile hepatocytes." (PMID 40963741, 2025).
osteosarcoma (3 papers, 2014 to 2026). A usually aggressive malignant bone-forming mesenchymal neoplasm, predominantly affecting adolescents and young adults. "The purpose of this experiment was to evaluate whether modified CAV2-AU-M2 retained the same infection efficiency, conditional replication, and oncolytic activity in canine osteosarcoma (OS) cell lines as its precursor, ICOCAV15." (PMID 38391964, 2024). "Our study demonstrates that CAV2-AU-M3 infects and lyses different canine OS cell lines at varying rates but produces anti-PD1 Ab at similar levels across all osteosarcoma cell lines." (PMID 42147185, 2026).
Stroke (3 papers, 2019 to 2022). Sudden impairment of blood flow to a part of the brain due to occlusion or rupture of an artery to the brain. "Jolobe (2012) found that recurrent stroke is because of a novel voltage sensor mutation in CAV2." (PMID 32038707, 2019). "Caveolin-1 and caveolin-2 can modulate the permeability of endothelium and blood-brain barrier after stroke and inhibit the release of free radicals." (PMID 33224083, 2020).
type 2 diabetes mellitus (3 papers, 2011 to 2021). A type of diabetes mellitus that is characterized by insulin resistance or desensitization and increased blood glucose levels. "Similarly, previous interaction findings for type 2 diabetes susceptibility genes, such as TCF7L2, GIPR, CAV2, and HFE, with other dietary factors were not replicated in the EPIC-InterACT study." (PMID 32722593, 2020).
amyotrophic lateral sclerosis (2 papers, 2020 to 2023). "There is converging evidence that CAV1 and CAV2 (CAV1/2) genes have a role in amyotrophic lateral sclerosis (ALS)." (PMID 36937187, 2023).
Arthritis (2 papers, 2020 to 2024). Inflammation of a joint. "Markedly, in contrast to neuropathic pain, the use of CaV2.2 directed agents for the treatment of arthritis-related pain has been limited both preclinically and clinically." (PMID 38895294, 2024).
Cerebral ischemia (2 papers, 2012 to 2016). Restriction of arterial blood supply to the brain associated with insufficient oxygenation to support the metabolic requirements of the tissue. "Next, they investigated the effects of cerebral ischemia in Cav-1 and Cav-2 KO mice and have shown marked increase of cerebral volume of infarction and elevated apoptotic index in Cav-1 KO relative to WT and Cav-2 KO mice." (PMID 26605130, 2012).
cystic fibrosis (2 papers, 2012 to 2015). Autosomal recessive disorder caused by pathogenic variants in the CFTR gene (cystic fibrosis transmembrane conductance regulator), which encodes a chloride and bicarbonate channel expressed in epithelial cells, and follow the diagnosis criteria. "Caveolin 2, which localizes to the Golgi complex but redistributes to plasma membrane, caveolae and rafts when co-expressed with caveolin 1, is a potential key molecule related to the Pseudomonas infection causing pneumonia in patients with cystic fibrosis and other immunocompromising conditions." (PMID 22330747, 2012). "Accordingly, we tested for association between CAV2 rs8940 and TMC6 rs34712518 cystic fibrosis-specific percentiles of forced expiratory volume at 1 second (FEV1)." (PMID 26047157, 2015). "We used exome sequencing to identify variants in CAV2 and TMC6 that modify the age-of-onset of chronic Pseudomonas aeruginosa infection among children with cystic fibrosis, and validated our findings in a large cohort of children with cystic fibrosis." (PMID 26047157, 2015). "Notably, CAV2 is among the genes identified by GeneGO in conjunction with the Cystic Fibrosis Foundation in the MetaMiner-CF database and network tool as potential modifier genes in CF based on its role in endosome formation in lung epithelial cells." (PMID 26047157, 2015).
deafness (2 papers, 2015 to 2018). An inherited or acquired condition characterized by the complete loss of the ability to hear from one or both ears. "The increased cav2 level contributed dramatically to the progression of the GJB2 –associated deafness." (PMID 29760588, 2018). "Investigation of these molecular pathways, including those involving CAV2, may contribute to our understanding of the pathogenesis of GJB2-associated deafness and provide new information on effective targets for new therapies." (PMID 26492081, 2015). "Investigation of these molecular pathways, including those involving CAV2, may contribute to the elucidation of a new pathogenic mechanism of GJB2-associated deafness and identify effective targets for new therapies." (PMID 26492081, 2015).
head and neck squamous cell carcinoma (2 papers, 2022 to 2023). A squamous cell carcinoma that arises from any of the following anatomic sites: lip and oral cavity, nasal cavity, paranasal sinuses, pharynx, larynx, and salivary glands. "In this study, we aimed to explore the pathogenic and prognostic roles of CAV1 and CAV2 in head and neck squamous cell carcinoma (HNSCC) through bioinformatic analysis and verified in human tissue." (PMID 36830672, 2023).
Hepatic fibrosis (2 papers, 2020 to 2021). The presence of excessive fibrous connective tissue in the liver. "Accordingly, we speculated CAV2 is implicated in miR-199a-3p-induced liver fibrosis, and explored the further mechanism." (PMID 32499481, 2020). "To clarify how miR-199a-3p involves in liver fibrosis by regulating CAV2, we attempted to define CAV2 function in HSC activation and liver fibrosis." (PMID 32499481, 2020). "Additionally, miR-455-3p reduces liver fibrosis and HSC activation by inhibiting the expression of HSF1, and miR-199a-3p exacerbates hepatic fibrosis by inhibiting the expression of caveolin-2 and triggering the TGF-β pathway." (PMID 34867446, 2021). "Here, we identified that CAV2 suppresses HSC activation and its anti-fibrotic role in liver fibrosis." (PMID 32499481, 2020).
lymph node metastases (2 papers, 2018 to 2022). "Loss of stromal CAV2 in the lymph node metastases was also significantly associated with earlier death (p = 0.011)." (PMID 29850392, 2018). "Comparison between the expression of stromal CAV2 of matched tumor and lymph node metastasis samples (n = 39) showed a concordance in 56.4% (n = 22)." (PMID 29850392, 2018). "When the stromal expression in matched primary tumors and lymph node metastases was compared, both CAV1 and CAV2 expressions were frequently found lost in the corresponding stroma of the lymph node metastasis (40.6%, p = 0.003 and 38.4%, p = 0.001, resp)." (PMID 29850392, 2018). "Interestingly, 75.0% (n = 27) of the patients that died during the study period had no CAV2 expression in the stroma of lymph node metastases, whereas 83.3% of the patients who were still alive were positive for CAV2 (p = 0.011)." (PMID 29850392, 2018).
migraine (2 papers, 2018 to 2023). "Some agents employed to treat hemiplegic migraine include calcium channel blockers like flunarizine and verapamil (CaV1-blocking and potentially CaV2-blocking at higher doses)." (PMID 30080864, 2018).
normal tension glaucoma (2 papers, 2015 to 2016). "Further studies are warranted to investigate the associations of the CAV1/CAV2 SNPs with normal-tension glaucoma, which will further enrich our understanding of the roles of the CAV1/CAV2 locus in POAG." (PMID 27297022, 2016).
urothelial carcinoma (2 papers, 2011 to 2019). A malignant neoplasm derived from the transitional epithelium of the urinary tract (urinary bladder, ureter, urethra, or renal pelvis). "Although Cav-2 expression levels were unaltered by oncogenic transformation, Cav-2 expression was upregulated in esophageal and urothelial carcinoma." (PMID 22229094, 2011).
Alzheimer disease (1 paper, 2011). A progressive, neurodegenerative disease characterized by loss of function and death of nerve cells in several areas of the brain leading to loss of cognitive function such as memory and language. "Elevated levels of CAV-1 and CAV-2 have been associated with several forms of cancer, Alzheimer disease, and other human diseases." (PMID 22128235, 2011).
Anxiety (1 paper, 2025). Intense feelings of nervousness, tension, or panic often arise in response to interpersonal stresses. "Mg2+o reduces glutamatergic neurotransmission by blocking CaV2 channels on presynaptic neurons, alleviating anxiety, panic, and phobic reactions, and ameliorating sleeping deficits." (PMID 41465576, 2025).
autism (1 paper, 2021). Persistent deficits in social interaction and communication and interaction as well as a markedly restricted repertoire of activity and interest as well as repetitive patterns of behavior. "Our previous studies identified a synaptic retrograde signal mediated by autism-linked proteins that regulate CaV2 presynaptic localization to alter excitatory synaptic transmission." (PMID 33787493, 2021).
cardiac hypertrophy (1 paper, 2019). "Cav1 Cav3 double knockout animals, which completely lack caveolins because CAV2 is degraded in the absence of CAV1, develop cardiac hypertrophy and contractile failure." (PMID 31782728, 2019).
cardioembolic stroke (1 paper, 2019). "CAV1, SURF1, PLEKHH2, ECD, BNIP1, CAV2 are found to be associated with cardioembolic stroke and Small vessel stroke in Europeans." (PMID 32038707, 2019).
chlamydial infection (1 paper, 2011). "The role of noncaveolar Cav-2 was also suggested in chlamydial infection of various epithelial cell lines including HeLa and FRT cells, where Cav-2 associated with the chlamydial inclusion independently of Cav-1." (PMID 22229094, 2011).
Cirrhosis (1 paper, 2015). A chronic disorder of the liver in which liver tissue becomes scarred and is partially replaced by regenerative nodules and fibrotic tissue resulting in loss of liver function. "We found also increased expression of caveolin-1 and caveolin-2 in blood in the group of patients with cirrhosis." (PMID 26317806, 2015).
co-infection (1 paper, 2024). "The positivity rates and co-infection rates of CCoV, CRCoV, CAV-2, and CNV in the 1688 clinical samples in this study confirmed the necessity of this quadruplex RT-qPCR assay." (PMID 39770314, 2024). "Since the co-infections of other multiple pathogens besides CCoV, CRV, CPV, and CDV in clinical sick cases, the quadruplex RT-qPCR for the detection of CCoV, CRCoV, CAV-2, and CNV was developed in this study to meet the needs of clinical testing and diagnosis." (PMID 39770314, 2024). "In addition, it has shown that two or more of CCoV, CRCoV, CAV-2, and CNV can be detected simultaneously in dogs with different clinical signs, and co-infections of these pathogens exacerbate the seriousness of the diseases." (PMID 39770314, 2024).
depression (1 paper, 2018). "These experiments also demonstrate that the inhibition of the CaV2 calcium current is at least partially responsible for the inhibition of neurotransmitter release with heterosynaptic depression." (PMID 29459734, 2018). "As the CaV2 calcium current triggers action potential evoked neurotransmitter release and 5HT1A activation strongly reduces transmitter release we examined the role of Y1501F on heterosynaptic depression." (PMID 29459734, 2018).
endothelial dysfunction (1 paper, 2020). In vascular diseases, endothelial dysfunction is a systemic pathological state of the endothelium (the inner lining of blood vessels) and can be broadly defined as an imbalance between vasodilating and vasoconstricting substances produced by (or acting on) the endothelium. "Its upregulation in pulmonary arteries induced ROS and led to direct targeting of SOD1, and downregulation of its other predicted target genes such as connexin-43 (Cx43), KLF4 and caveolin 2 (CAV2) mRNA leading to endothelial dysfunction." (PMID 32962281, 2020).
endotoxemia (1 paper, 2017). "In conclusion, Cav-1−/− and Cav-2−/− mice show opposing outcomes in LPS-induced endotoxemia." (PMID 29250058, 2017).
hemorrhage (1 paper, 2020). Loss of blood from the vascular compartment to the exterior or into nonvascular body space as a result of rupture or severance of the blood vessels. "Both the serum levels of caveolin-1 and caveolin-2 in hemorrhage group (0.14 ± 0.025 and 0.46 ± 0.043 ng/ml, respectively) are lower than in non-hemorrhage group (0.39 ± 0.046 and 0.47 ± 0.051 ng/ml, respectively)." (PMID 33224083, 2020). "Our results showed that the non-hemorrhage group of patients presented significantly higher caveolin-1 and caveolin-2 levels than the hemorrhage group of patients after intravenous thrombolysis treatment." (PMID 33224083, 2020).
Hepatic steatosis (1 paper, 2016). Steatosis is a term used to denote lipid accumulation within hepatocytes. "Alike, miR-26b-5p influences translation of caveolin 2 and diacylglycerol O-acyltransferase 1, i.e. a key enzyme in hepatic steatosis in addition to lecithin-cholesterol acyltransferase which catalyzes its esterification for cholesterol transport." (PMID 27045805, 2016).
hypertrophic cardiomyopathy (1 paper, 2020). A condition in which the myocardium is hypertrophied without an obvious cause. "Knockout mice for caveolin-1, caveolin-2, and caveolin-3 develop hypertrophic cardiomyopathy with increase in fibrosis." (PMID 32626662, 2020).
injury (1 paper, 2015). Damage inflicted on the body as the direct or indirect result of an external force, with or without disruption of structural continuity. "It was also reported that CAV1 and CAV2 levels are elevated in endothelial cells in a mouse model of traumatic brain injury." (PMID 26492081, 2015).